CCL2 (C-C motif chemokine ligand 2)
Diseases named in the same sentence as CCL2 in open-access papers (continued):
Sharing a sentence is not in itself a finding about the gene and the disease.
glioblastoma (continued). "One of the most important chemoattractants known to recruit GAMs is the monocyte chemoattractant protein (MCP)-1 (alternative name: C-C motif ligand 2 (CCL2)), which is secreted by astrocytoma and glioblastoma cells in vitro and in vivo." (PMID 29389898, 2018). "Whole-genome expression analyses identified chemokine (C–C motif) ligand 2 (CCL2) as the top-listed NF-κB-regulated gene that was increased in glioblastoma cells by Smac mimetic treatment." (PMID 29371590, 2018). "We identified a six gene cytokine-related signature (CCL2, CCR2, CXCL10, IL10RB, IL17B, and IL17R) capable of dividing glioblastoma patients into a low risk score group with favorable survival and a high risk score group with poor survival." (PMID 25978454, 2015). "Notably, in glioblastoma, heightened CCL2 expression aligns with diminished overall patient survival, hinting at its potential as a prognostic biomarker for adverse outcomes." (PMID 39706820, 2024). "In summary, our work reveals that glioblastoma cell glycolysis triggers the infiltration of macrophages into the TME via upregulating LDHA-regulated CCL2/CCL7, and reciprocally, macrophages promote tumor growth and survival via EVs delivering LDHA to glioblastoma cells." (PMID 38443336, 2024). "Since LDHA, CCL2 and CCL7 are genes encoding secreted proteins, we compared their protein levels in patient plasma showing that all of them were higher in glioblastoma patients than that in healthy controls, but such levels were not changed in meningioma patients." (PMID 38443336, 2024). "In addition, a recent clinical trial used CCL2 expression level as a secondary measure of efficacy for glioblastoma patients' treatment using Salovum egg yolk powder (ClinicalTrials.gov, Identifier: NCT04116138)." (PMID 39030882, 2024). "It has been proposed that tumor-associated mesenchymal stem-like cells could play an important role in glioblastoma ECM remodeling through CCL2/JAK1/MLC2 signaling." (PMID 36980765, 2023). "Glioblastoma cells can themselves produce CCL2 and GM-CSF and promote the attraction of TIM." (PMID 35884700, 2022). "Furthermore, β-catenin knockdown decreased CCL2 secretion of glioblastoma cell lines, while CCL2 knockdown modulates β-catenin- and EMT-related genes." (PMID 35562953, 2022). "We previously reported that the CCL-2/CCR2 axis was involved in the biopsy-induced recruitment of inflammatory monocytes to GL261 glioblastoma as CCL-2 antibodies could be used to block their recruitment." (PMID 35883641, 2022). "CCL2 expression has been detected in a plethora of cancer types including glioblastoma." (PMID 33803414, 2021). "Furthermore, CD133+ glioblastoma stem cells exhibited the ability to recruit hUCBMSCs, which can further promote tumor growth in vivo, via exosomes containing MCP-1/CCL2 and SDF-1/CXCL12." (PMID 33849537, 2021). "Furthermore, overexpression of CCL2 in glioblastoma rodent models showed that CCL2 increased the amount of infiltrating TAMs." (PMID 32668709, 2020). "In addition, several studies have shown that an overexpression of CCL2 is correlated with metastasis and tumorigenesis in a variety of cancers, including breast cancer and glioblastoma." (PMID 31207928, 2019). "We have found that there is a significant correlation between the expression of CTRP1 and CCL2 in human glioblastoma; thus we further investigated if knockdown of CTRP1 could influence CCL2 expression." (PMID 31183364, 2019).
glioblastoma (continued). "In glioblastoma multiforme, Ccl2 is important for Treg recruitment into the brain and may perform a similar function after MPTP intoxication." (PMID 29783988, 2018). "In contrast, CCL2 expression has been found to be increased in malignant glioma, primary and metastatic melanoma and glioblastomas and astrocytomas compared to corresponding normal tissues." (PMID 15900302, 2005). "Furthermore, increased expression of CCL2 has been noted in human glioblastoma multiforme stem cells characterized by a mesenchymal-immune signature, which may contribute to the elevation of M-MDSCs in glioblastoma multiforme." (PMID 41368628, 2025). "In addition, CCL2, a chemokine secreted by tumor cells and stromal cells, mediates the recruitment of monocytes and neutrophils, which verified that blocking CCL2 can reduce the percentage of glioblastoma migration." (PMID 38578317, 2024). "Indeed, in glioblastoma, CCL2, CCL7, and CCL17 were notably increased." (PMID 36980182, 2023). "As An et.al demonstrated that EGFR cooperated with EGFRvIII to induce CCL2-mediated TAMs recruitment in GBM, we investigated CCL2 expression in glioblastoma cells under TMZ treatment." (PMID 36230833, 2022). "RNA interference of both β-catenin and CCL2 in GBM cells reduced migration of CD14+-monocytes towards TCM of glioblastoma cells." (PMID 35562953, 2022). "In contrast, glioblastoma tumour cells may be the main source of CCL2, CXCL10 and CXCL12 production in the tumour microenvironment given the elevated CCL2 detected in GNS cell culture supernatants and the minimal levels of CXCL10 and CXCL12 detected in dissociated tumour supernatants." (PMID 35464424, 2022). "Thus, our findings now suggest that high CCL2 abundance identified by multiple glioblastoma studies may mediate trafficking to glioblastoma through CCR2 rather than CCR4." (PMID 35464424, 2022). "This hypothesis is supported by a study where G261 mouse glioblastomas grown on a CCL2‐deficient background failed to recruit immunosuppressive myeloid cells, and the finding that CCL2 was associated with increased recruitment of T regulatory cells." (PMID 29888503, 2018). "A recent study has shown that the long non-coding RNA (LncRNA) H19 encodes an immune-related protein, H19-IRP, which promotes immunosuppression in glioblastoma multiforme (GBM) by binding to and activating the transcription of the CCL2 and galactaglutinin-9 promoters." (PMID 40297808, 2025). "Given the critical role of inflammatory cytokines in the glioblastoma tumor microenvironment (TME), we examined CCL2, another key mediator of tumor progression." (PMID 40149846, 2025). "Mechanistically, LDHA-lactate-directed ERK pathway activates YAP1 and STAT3 transcriptional co-activators to upregulate CCL2 and CCL7 in glioblastoma cells, which promote macrophage infiltration into the TME." (PMID 38443336, 2024). "Together, these findings suggest that YAP1 and STAT3 transcriptional co-activators contribute to LDHA/lactate–ERK axis-dependent CCL2 and CCL7 expression in glioblastoma cells." (PMID 38443336, 2024). "Here, we further identified that YAP1 activation promotes macrophage infiltration via direct transcriptional regulation of CCL2 and CCL7 in glioblastoma cells, consistent with the findings observed in liver cancer." (PMID 38443336, 2024). "MSCs are recruited at the tumor site in response to various chemokines, such as CCL2 or CXCL12, secreted by CD133+ tumor stem cells, as demonstrated in mice bearing glioblastomas." (PMID 39335210, 2024). "in 2021 found that the prognosis of glioblastoma (GBM) can be determined by seven differentially expressed genes (DEGs) 47, namely CLEC5A, HOXC6, HOXA5, CCL2, GPRASP1, BSCL2, and PTX3." (PMID 39132508, 2024). "In exploring the connection between LDHA and macrophage biology, we demonstrated that glioblastoma cell LDHA upregulates multiple downstream chemokines, most prominently CCL2 and CCL7, to trigger macrophage infiltration, consistent with previous work." (PMID 38443336, 2024).
glioblastoma (continued). "In summary, these results reinforce that the expression of CCL2 and CCL7 in glioblastoma cells/GSCs is regulated by LDHA and that glioblastoma cell CCL2 and CCL7 function as potent macrophage chemoattractants." (PMID 38443336, 2024). "The authors also found that GBM patients who had a low expression of CCL2 (monocyte chemoattractant protein) had a significant prolonged survival, inhibiting the CCL2-CCR2 axis in glioblastoma-bearing mice significantly increased their survival." (PMID 37274252, 2023). "For example, monocyte migration is driven by the monocyte chemoattractant protein CCL2 via the CCR2 receptor, and CCL2 downregulation resulted in reduced monocyte migration and prolonged survival in a murine model of glioblastoma." (PMID 36768342, 2023). "C1q/TNF-related protein 1 (CTRP1), a member of the CTRP family, is strongly correlated with glioblastoma multiforme (GBM) and can regulate CCL2 expression, promoting tumor progression." (PMID 37033981, 2023). "The chemokine genes MIF, CCL2, CXCL8, CX3CL1 and CXCL2 were all highly expressed by the six glioblastoma primary lines." (PMID 36430641, 2022). "Colony-stimulating factor 1 (CSF-1) and chemokine (C-C motif) ligand 2 (CCL2), which are overexpressed in glioblastoma, attract macrophages and determine their behavior." (PMID 35406398, 2022). "Previous studies indicated strong overexpression of IL-6, IL-10, VEGF, GM-CSF, and CCL2 in human GBM specimens, and the level of overexpression strongly correlated with tumor grade, proliferation markers, and clinical aggressiveness in glioblastomas." (PMID 35884700, 2022). "The first experiment evaluated the chemoattraction potential of the chemoattractants CXCL10, CCL2, CCL11 individually and in combination on two established glioblastoma cell lines: F98 and U87MG." (PMID 34830041, 2021). "In the present study, we surveyed and demonstrated the potency of the chemokines CXCL10, CCL2 and CCL11 to attract neoplastic glioblastoma cells in vitro and in vivo." (PMID 34830041, 2021). "Within the glioblastoma TME, GAMs and tumour cells have been identified as the main sources of CCL2, though evidence suggests GAM-secreted CCL2 has a more significant impact, possibly due to higher levels being produced." (PMID 33803414, 2021). "Of note, in a mouse model of glioblastoma, CX3CR1 deficiency led to increased CNS infiltration of CCR2+ monocytes into the tumor tissue, and it was suggested that this could be linked to increased microglial IL-1β, which in turn could induce CCL2 by tumor cells." (PMID 28320442, 2017). "In vitro, long noncoding RNA H19 (H19-IRP) promotes glioblastoma multiforme (GBM) immunosuppression by binding to CCL2 and galectin-9 promoters to activate its transcription and recruiting myeloid-derived suppressor cells (MDSCs) and TAMs to induce T cell exhaustion and an immunosuppressive GBM-TME." (PMID 41341593, 2025). "CSC actively recruit Treg cells to the tumour microenvironment through the secretion of chemokines, such as CCL1, CCL2, and CCL5, a process that has been validated in a mouse glioblastoma model, in which CCL2 relies on the expression of CCR4 to mediate the Treg cell trafficking." (PMID 39184916, 2024). "Moreover, treatment with EMφ EVs upregulated the levels of P-ERK, YAP1, P-STAT3, CCL2, and CCL7 in glioblastoma cells." (PMID 38443336, 2024). "Moreover, plasma LDHA correlated positively with plasma CCL2 and CCL7 and intratumoral macrophages in glioblastoma." (PMID 38443336, 2024). "Moreover, bioinformatics analyses in TCGA glioblastoma dataset confirmed that LDHA, YAP1, STAT3, CCL2, and CCL7 positively correlated with each other and with macrophage signature in patient tumors." (PMID 38443336, 2024). "Furthermore, it has been shown that BM-MSCs promote senescence of the U87 glioblastoma cell line by inducing changes in cell morphology and by increasing the production of cytokines (IL-6, IL-8, leukemia inhibitory factor (LIF), CCL2/MCP-1, and CXCL2)." (PMID 38607056, 2024).
glioblastoma (continued). "To confirm the role of LDHA in regulation of the YAP1/STAT3–CCL2/CCL7 signaling axis in vivo, we performed immunofluorescence for YAP1 and STAT3 in tumors and ELISA for CCL2 and CCL7 in plasma from control and LDHA-inhibited glioblastoma tumor-bearing mice." (PMID 38443336, 2024). "Additionally, researchers have investigated the resistance mechanism of bevacizumab in the treatment of glioblastoma (GBM) and found that GBM cells secrete two cytokines, IL-8 and CCL2, which stimulate TAMs to produce TNFα, which activates endothelial cells (ECs)." (PMID 38787372, 2024). "The results indicated that the expression of C1R, CCL2, and TNFRSF1A might promote the development of glioblastoma and might be used as molecular biomarkers of prognosis and immune infiltration in GBM patients in the future." (PMID 35726234, 2022). "We also observed high levels of CCL2 in supernatants from dissociated glioblastoma biopsies and GNS cells, inferring that CCL2 could recruit T cells through CCR2 or CCR4 to glioblastoma." (PMID 35464424, 2022). "The results suggested that the expression of C1R, CCL2, and TNFRSF1A might promote the development of glioblastoma." (PMID 35726234, 2022). "We also identify CCL2 and CCL7 as predictors of survival in human glioblastoma." (PMID 36685592, 2022). "Since the EGFR signaling pathway has been reported to induce CCL2 expression to recruit macrophages in glioblastoma, we propose that ADAM8 could induce TAM recruitment by regulating CCL2 expression via HB-EGF/EGFR." (PMID 36230833, 2022). "There, genes with a higher expression in glioblastoma compared to astrocytoma were VEGFA, 4EBP1, CCL2, PLAU (uPA), CXCL8 (IL8), CXCL10 (IP10), CASP8, HGF, LIF, CD40, CDCp1, TNFRSF11B (OPG), CD274 (PD-L1), IL6, CXCL1, CCL20 (MIP3α), CCL8 (MCP2), CD244, MMP1, TNFRSF9, CXCL6, MMP10, FGF5)." (PMID 35301393, 2022). "A CCL2 inhibitor, mNOX‐36 suppressed TAM recruitment in a rat glioblastoma multiforme model." (PMID 34464477, 2021). "Meanwhile, K-M curves confirmed that these three genes (CCL2, IGFBP2, and PDPN) could be used as independent predictors of survival in patients with glioblastoma." (PMID 32296458, 2020). "The secretion of CCL2 and CCL22 in glioblastoma tumour cells could facilitate infiltration and recruitment in the TME." (PMID 30777100, 2019). "Furthermore, survival was longer in the Il-6 knockout mice relative to wild-type mice, which was not the case when SB28 glioblastoma was implanted into C57BL/6J Ccl2 or Cxcl10 knockout mice." (PMID 40161763, 2025). "To further investigate whether LDHA-regulated lactate contributes to this process, we treated LDHA-depleted glioblastoma cells with lactate and found that this treatment rescued the impaired signaling of P-ERK, YAP1, P-STAT3, CCL2, and CCL7 in shLdha CT2A cells." (PMID 38443336, 2024). "To detect the expression levels of C1R, CCL2, and TNFRSF1A in glioblastoma, we analyzed the mRNA levels of GBM patients and glioblastoma cells." (PMID 35726234, 2022). "Moreover, glioblastoma cells can produce kynurenine that activates AHR in TAMs; AHR recruits TAMs through CCR2/CCL2, drives the expression of the ectonucleotidase CD39 in TAMs, and plays a synergistic role with CD73 to promote adenosine production, leading to CD8+ T-cell dysfunction." (PMID 36466873, 2022). "For example, co-culture of various types of cancer cells, including HCC and glioblastoma with CSC-conditioned media, promoted the release of numerous chemokines and cytokines favoring tumorigenic macrophage factors, including CCL2, CCL5, CSF1, GDF-15, IL-13, TGF-β, and WISP1." (PMID 34831048, 2021).
glioblastoma (continued). "Furthermore, in all types tested, i.e., oligodendroglioma WHO grade II, anaplastic oligoastrocytoma WHO grade III, and glioblastoma WHO grade IV, expression level of CCRL2 correlated significantly in a similar way with the expression of its potential ligands, CCL2 and CCL5." (PMID 32456359, 2020). "This tropism may be related to the monocyte chemoattractant protein 1 (MCP-1)/CC motif chemokine ligand 2 (CCL2) and stromal cell-derived factor-1 (SDF-1)/CXC motif chemokine ligand 12 (CXCL12) chemokines, which mediate MSC migration to CD133+ glioblastoma cells in vitro." (PMID 35741334, 2022). "Similarly, in several experimental glioblastoma models, tumor cells released CCL2 to attract macrophages, and the blockade of CCL2/CCR2 prolonged mouse survival in GBM models." (PMID 36230833, 2022). "Moreover, the mRNA expression levels of C1R, CCL2, and TNFRSF1A in glioblastoma cells or in GBM patients were found to be strongly upregulated, and the mRNA expression levels of these three genes were positively associated with each other." (PMID 35726234, 2022). "The decreased P-ERK, YAP1, P-STAT3, CCL2, and CCL7 in LDHA-depleted glioblastoma cells was rescued by the treatment with EMφ EVs, but not LDHA-depleted EMφ EVs." (PMID 38443336, 2024). "Also paracrine effects on the tumor microenvironment might contribute to this effect, as co-culture experiments revealed that Smac mimetic-treated glioblastoma cells can stimulate the migration of non-malignant astroglial cells toward glioblastoma cells via secretion of CCL2 by glioblastoma cells." (PMID 29371590, 2018). "Moreover, plasma LDHA, CCL2, and CCL7 levels were not related to the status of recurrence, gender, age, and MGMT methylation in glioblastoma patients." (PMID 38443336, 2024). "Although targeting CCL2-mediated recruitment of MDMs has not yet been clinically explored, combining CCL2 inhibition with anti-PD-1 treatment prolonged survival in GSC glioblastoma-bearing mice, and may be a potential candidate for future studies." (PMID 34054867, 2021).